LRFN4 (leucine rich repeat and fibronectin type III domain containing 4)
Description:
Promotes neurite outgrowth in hippocampal neurons. May play a role in redistributing DLG4 to the cell periphery (By similarity).
Synonyms: SALM3; MGC3103; SALM3.; FIGLER6
Tractability: Antibody: its Gene Ontology location is reachable by antibodies, with high confidence; UniProt predicts a signal peptide or a membrane-spanning region. PROTAC: its protein half-life has been measured.
Gene: Protein-coding gene on chromosome 11 (66,856,546 to 66,860,475, forward strand). Ensembl gene ENSG00000173621.
Subcellular location: Membrane
Pathways (Reactome):
Neuronal System: Synaptic adhesion-like molecules
Gene Ontology:
Molecular function: protein binding
Biological process: regulation of postsynaptic density assembly; regulation of presynapse assembly; synaptic membrane adhesion
Cellular component: cell surface; glutamatergic synapse; plasma membrane; postsynaptic density membrane; GABA-ergic synapse; membrane
Genetic constraint (gnomAD): Loss-of-function variants: 12 observed, 24.15 expected, observed/expected ratio (o/e) 0.5, 90% interval 0.32 to 0.81. The synonymous counts are far from expectation, so gnomAD's model fits this gene poorly and the ratio says little. Missense variants: 850 observed, 798.35 expected, observed/expected ratio (o/e) 1.06, 90% interval 1.01 to 1.13. Synonymous variants: 493 observed, 386.67 expected, observed/expected ratio (o/e) 1.27, 90% interval 1.18 to 1.37.
Homologues: Orthologues: chimpanzee LRFN4 (99% identical), macaque LRFN4 (99% identical), pig LRFN4 (99% identical), dog LRFN4 (98% identical), guinea pig LRFN4 (97% identical), mouse Lrfn4 (97% identical), rat Lrfn4 (97% identical). Paralogues in human: LRFN2 (56% identical), LRFN3 (51% identical), LRFN1 (49% identical), LRFN5 (47% identical), LRRN2 (23% identical), LRRN1 (22% identical), SLIT2 (22% identical), SLIT1 (21% identical), SLIT3 (21% identical), LINGO1 (20% identical), LRRN3 (20% identical), LINGO2 (20% identical), and 13 more.